LINC00052 (long independently transcribed non-coding RNA 52)
Synonyms: NCRNA00052; TMEM83; FLJ31461
Gene: Long non-coding RNA gene on chromosome 15 (87,576,927 to 87,579,866, forward strand). Ensembl gene ENSG00000259527.
Subcellular location: Membrane
Diseases named in the same sentence as LINC00052 in open-access papers:
LINC00052 is named in the same sentence as 10 diseases in open-access papers, as found by Europe PMC text mining. Sharing a sentence is not in itself a finding about the gene and the disease. The quoted sentences say what the papers report.
breast carcinoma (2 papers, 2017 to 2024). "Similarly, our research group showed that LINC00052 is associated with improved overall survival in breast cancer patients and that LINC00052 inhibits BC cell migration through modulation of the cytoskeleton and NOTCH/β–catenin/NFkB signalling pathways." (PMID 38832821, 2024). "The understanding of the role of LINC00052 in breast cancer is currently limited, and there is some contradictory data." (PMID 38832821, 2024). "In this regard, LINC00052 acts as a suppressor gene, at least in hepatocarcinoma, pancreatic cancer, gliomas, and possibly breast cancer, while remarkably, it appears to function as an oncogene in gastric cancer." (PMID 38832821, 2024). "Our research group found that LINC00052 expression was repressed during the formation of breast cancer (BC) multicellular spheroids." (PMID 38832821, 2024). "In accordance, Pacheco-Marin and Muñoz-Galindo also reported decreased levels of LINC00052 in three-dimensional breast cancer multicellular spheroids, which mimics the biology of avascular tumours in vivo, as the cells become more aggressive." (PMID 38832821, 2024). "In contrast, LINC00052-silencing resulted in diminished HER3 expression and cell growth suggesting that LINC00052 exerts an important role for HER3 regulation in HER3-enriched breast cancer cells." (PMID 28036286, 2017). "We sought to investigate a possible role of LINC00052 in the regulation of HER3 expression in breast cancer cells." (PMID 28036286, 2017). "We observed that elevation of LINC00052-ectopic expression leads to better response of breast cancer cells to HER3-targeting antibody treatment, suggesting clinical relevance of LINC00052 as a potential biomarker for HER3-targeting therapies." (PMID 28036286, 2017). "To further confirm the correlation between HER3 and LINC00052 expression, we established breast cancer cells stably expressing ectopic-HER3." (PMID 28036286, 2017). "We observed that high LINC00052 expression is associated with increased survival in patients with luminal A, ER+, PR+ and TNBC breast cancer, data consistent with previous reports that showed that high LINC00052 expression is associated with greater overall survival in BC patients." (PMID 38832821, 2024). "The expression and regulation of LINC00052 could open up interesting new perspectives for the understanding of HER3 regulation in breast cancer." (PMID 28036286, 2017). "To understand whether LINC00052 expression promotes growth of breast cancer cells in a high HER3 context, we investigated the function of LINC00052 in MCF7 breast cancer cells stably expressing LINC00052-silenced shRNA, ectopic LINC00052, in comparison with controls." (PMID 28036286, 2017). "However, additional mechanistic studies of LINC00052 chromatin modifications will be necessary to investigate the role of its in the regulation of HER3 in breast cancer subtype these modifications might occur." (PMID 28036286, 2017). "Here, we describe for the first time a regulatory interplay between the long noncoding RNA designated as LINC00052 and HER3 expression in breast cancer cells." (PMID 28036286, 2017). "Interestingly, when LINC00052 expression is inhibited, ‘Pro-oncogenic action of estradiol_estrogen receptors’ as well as ‘ESR1/ESR2 ratio in breast cancer’ signalling pathways are modulated." (PMID 38832821, 2024). "Furthermre, we observed that LINC00052-ectopic fails to increase the cell growth of breast cancer MCF7 when HER3 is silenced by shRNA, suggesting that LINC00052 promotes cell growth by increasing HER3 expression." (PMID 28036286, 2017). "LINC00052, with previously unknown function, is significantly reduced in HER3-knockdown MCF7 breast cancer cells in comparison with the control cells as indicated by two independent probes (8.1 and 5.8 fold change of mRNA levels for probe 1 and probe 2, respectively, p ≤ 0.0001)." (PMID 28036286, 2017).
gastric cancer (2 papers, 2020 to 2024). A primary or metastatic malignant neoplasm involving the stomach. "LINC00052 promotes gastric cancer progression by activating the Wnt signaling pathway." (PMID 33231561, 2020).
hepatocellular carcinoma (2 papers, 2016 to 2020). A malignant tumor that arises from hepatocytes. "For example, LINC00052 increases EPB41L3 to repress hepatocellular carcinoma migration and invasion by binding miR-452-5p." (PMID 33231561, 2020). "In our study, we discovered LINC00052 through Gene trap technology and we found that LINC00052 expressed in the cytoplasm and could affect hepatoma cells invasion and migration." (PMID 27351280, 2016).
head and neck carcinoma (1 paper, 2022). A carcinoma that arises from the head and neck region. "Previous reports have suggested that LINC00052 is linked to EMT, cancer cell migration, progression and invasion in hepatocellular and head and neck carcinoma." (PMID 36552797, 2022).
pancreatic cancer (1 paper, 2021). "LINC00052 functions as a tumor suppressor through modulating miR-330-3p in pancreatic cancer." (PMID 33865422, 2021).
triple-negative breast carcinoma (1 paper, 2017). An invasive breast carcinoma which is negative for expression of estrogen receptor (ER), progesterone receptor (PR), and human epidermal growth factor receptor 2 (HER2). "LINC00052 has been found expressed in human non-triple negative breast cancer subtypes." (PMID 28036286, 2017).
cancer (7 papers, 2017 to 2024). A tumor composed of atypical neoplastic, often pleomorphic cells that invade other tissues. "These authors also found that LINC00052 promotes cancer growth by activating the HER3 signalling pathway." (PMID 38832821, 2024). "LINC00052 function has been a topic of debate, as it has been found to act as a cancer promoter and a tumour suppressor in different tumour types." (PMID 38832821, 2024). "Several studies have demonstrated that LINC00052 is involved in tumorigenesis, progression, and metastasis in several types of human cancers." (PMID 36836780, 2023). "Linc00052 is involved in the regulation of cancer progression and inflammation." (PMID 35473503, 2022). "Previous studies have demonstrated the oncogenic roles of linc00052 in various cancers; however, its role in RA remains unclear." (PMID 35473503, 2022). "Whereas LINC00052 has been recently associated with certain cancers, no disease associations have been detected, to the best of our knowledge, for AF131216.7 and RP11-739B23.1." (PMID 31927529, 2020). "Taken together, our results indicate that high LINC00052 levels predict activation of HER3-mediated signaling, and LINC00052 expression level may serve as a potential biomarker for HER3 targeted antibody cancer therapies." (PMID 28036286, 2017).
tumor (6 papers, 2016 to 2024). "LINC00052 has been shown to serve as either tumor suppressors or oncogenic factors, with their specific functions depending on diverse biological processes." (PMID 28969024, 2017). "LINC00052 has been recognized as a crucial regulator of tumor processes." (PMID 33231561, 2020). "Our results indicated that although overexpression of LINC00052 suppressed tumor cell proliferation, migration and invasion, upregulated miR-452-5P could largely rescue these effects." (PMID 28969024, 2017). "Our results elucidated that LINC00052 might have a tumor suppressor function in HCC and could be a novel potential target for therapy of HCC." (PMID 27351280, 2016). "Taken these results together, we concluded that LINC00052 could influence tumor proliferation in vivo." (PMID 27351280, 2016). "Taken these results together, we concluded that LINC00052 could influence tumor migration in vivo." (PMID 27351280, 2016). "In this study, we found that overexpression of LINC00052 could upregulate the EPB41L3 expression and it might serve as a tumor suppressor gene in HCC." (PMID 28969024, 2017). "LINC00052 depletion could promote cell proliferation, colony formation, migration and invasion in HCC cell lines in vitro and our previous studies demonstrated that LINC00052 knockdown promoted tumor growth and metastasis in vivo." (PMID 28969024, 2017).
LINC00052 also shares sentences with these, for which no sentence is quoted: kidney chromophobe (1 paper); lung squamous cell carcinoma (1).